STAT3 (signal transducer and activator of transcription 3)
Diseases named in the same sentence as STAT3 in open-access papers (continued):
Sharing a sentence is not in itself a finding about the gene and the disease.
cancer (continued). "Finally, miR-125a suppresses metastasis and cisplatin resistance in several types of cancer through repression of c-Myc, matrix metalloproteinase (MMP)-2, and MMP-9 by directly inhibiting STAT3 expression." (PMID 31952344, 2020). "Interestingly, our results showed that IL-6 secreted by MSCs leads to STAT3 activation and upregulation of CD73 expression in cancer cells, promoting xenograft NPC growth and resistance to cisplatin treatment." (PMID 32127934, 2020). "Constitutive expression of STAT3 in cancer stem cells independent of upstream signaling regulators confirms the validity of targeting STAT3 in those cells." (PMID 33158194, 2020). "The mechanism may be related to Leptin/STAT3 signal transduction, VEGF-A, VEGFR-1 and WCAF target proteins related to cancer immune such as leptin and AKT1." (PMID 33746736, 2020). "Signal transducer and activator of transcription 3 (STAT3) is a ubiquitous and pleiotropic transcription factor that plays essential roles in normal development, immunity, response to tissue damage and cancer." (PMID 32123861, 2020). "Finally, the STAT3-dependent overexpression of S100A8 and S100A9 proteins, which are important mediators in cancer-induced inflammation, prevents also the normal differentiation of myeloid progenitor cells, promoting their conversion in functional MDSCs." (PMID 33584695, 2020). "STAT3 can activate transcription in the absence of tyrosine phosphorylation by interacting with nuclear factor-κB (NF-κB) subunits to induce specific cancer genes." (PMID 33371351, 2020). "A similar data was previously reported in which Apigenin decreased the expression of phospho Janus Kinase 1/2 (phospho-JAK1/ JAK2), phospho-STAT3, and STAT3-dependent luciferase reporter gene activity in human epidermal growth factor receptor 2 (HER2)- expressing BT- 474 cancer cells." (PMID 32952942, 2020). "These anti-cancer effects may potentially result from inhibition of EGFR and downregulation of the PI3K/AKT/mTOR, NF-κB, and STAT3 signaling pathways." (PMID 32328465, 2020). "The remainder of this review will focus on direct STAT3 inhibitors that have advanced into clinical trials with promising therapeutic potential as monotherapy or in combination with other treatment modalities in HCC and other cancers." (PMID 31731457, 2019). "Both STAT3 canonical and non-canonical signaling pathways are involved in the development and differentiation of several cancer types." (PMID 31500219, 2019). "Clinically, increasing evidence indicates that the activation of the STAT3/STAT5 pathway has significant correlation with reduced survival of recurrent EOC, suggesting the importance of STAT3/STAT5 as potential therapeutic targets for cancer therapy." (PMID 31861720, 2019). "Therefore, metformin appears to exert its effect on cancer cells not only by inhibiting ERK and STAT3 signaling, but also by reversing the downregulated PTPRD expression." (PMID 31805999, 2019). "Accordingly, HSP90 inhibition leads to RTK destabilization and absence of STAT3 activation in different models of cancer." (PMID 31861612, 2019). "STAT3 and STAT5 have essential roles in regulating cancer stem cells (CSCs) of EOC." (PMID 31861720, 2019). "In contrast, proteins that promote various cancer malignant properties, including CCND1, ERBB2, SNAIL, SLUG, phosphorylated STAT3 (p-STAT3), FAK, FOXM1, ETS1, YAP, HES1, and OCT4, were all significantly downregulated, an indication of reduction of malignancy in the cancer cells after EZH2 knockdown." (PMID 31130994, 2019). "Inhibition of STAT3 activation can also lead to the inhibition of AKT activation, which was also reflected our findings, indicating the potential involvement of multiple signaling pathways in the anti-cancer activity of arnicolide D." (PMID 31108969, 2019).
cancer (continued). "With respect to STAT3, constitutive is observed in > 70% of human cancers and has been found to be a negative prognostic indicator for several of these." (PMID 31409327, 2019). "Furthermore, a small-molecule inhibitor of STAT-3, BBI608, has been reported to significantly inhibit cancer stemness in a variety of cancer types, including PDAC." (PMID 31108941, 2019). "These indicate the feasibility of STAT3 inhibition with OPB-111077 but more trials are essential for assessing its safety, pharmacokinetics and therapeutic efficacy in larger cohorts of patients with HCC or other cancer types." (PMID 31731457, 2019). "The IL-6/JAK1/2/STAT3 signaling pathway plays an important role in the conversion of non-stem cancer cells (NSCCs) into CSCs." (PMID 31019654, 2019). "In cancer cells, STAT1 and STAT3 may interfere with each other, and perturbation of the balance of STAT1 and STAT3 levels is suggested as a novel therapeutic strategy for cancers." (PMID 30956773, 2019). "Pyk2 could regulate AKT, STAT3, ERK, MEK1/2, Src, HER3, MAPK, EGFR, and STAT5b in EGFR signaling in different cancer types." (PMID 31368612, 2019). "Mechanistically, through repressing NF-κB/RelA and STAT3, PDLIM2 increases expression of genes involved in antigen presentation and T-cell activation while repressing multidrug resistance genes and cancer-related genes, thereby rendering cancer cells vulnerable to immune attacks and therapies." (PMID 31757943, 2019). "The downregulation of IL-6 in CAFs mediated by shRNA failed to promote chemotherapeutic resistance and did not increase the activation of STAT3 in the cancer cells co-cultured with CAFs." (PMID 30927911, 2019). "Moreover, we show that the loss of p-STAT3 is accompanied by a decrease in the levels of gp130 and p-JAK2, two upstream regulators of p-STAT3 activity in breast (MDA-MB-231) and lung (A549) cancer cells." (PMID 31491838, 2019). "STAT3 also favors immunosuppressive functions of MDSCs by inducing the expression and the activity of IDO (Indoleamine 2,3-dioxygenase 1) in breast and liver cancers or arginase-1 in head and neck squamous cell carcinoma." (PMID 31480382, 2019). "Notably, it is reported that morusin suppressed cancer cell migration and regulated EMT markers by suppression of STAT3." (PMID 31067694, 2019). "Besides, the mRNA expression of matrix metalloproteinase-2 (MMP-2) and the vascular endothelial growth factor (VEGF) underwent down-regulation after STAT3 knockdown, demonstrating the pivotal role of STAT proteins in progression of cancer cells." (PMID 31569687, 2019). "DHTS deregulated the dynamic equilibrium from non-stem cancer cells to CSCs by dephosphorylating Stat3 and decreasing IL-6 secretion and inhibiting CSC formation." (PMID 31019654, 2019). "It has been documented that various transcriptional factors, such as STAT3, MYC, p65 and BRD4, could directly bind to the promoter of PD-L1 and regulate the transcription of PD-L1 in cancer cells." (PMID 30709380, 2019). "A number of anti-cancer compounds that inhibit STAT3 have been designed to date including Stattic, the first direct small molecular inhibitor, as well as LLL12, S31-201 and STA-21, in addition to the dual STAT3/STAT5 inhibitor SH-4-54." (PMID 31361777, 2019). "We hypothesized that EGFR downstream of STAT3 participates in HER3 expression because STAT3 contributes to cancer stemness and survival of EGFR-TKI resistant cancers." (PMID 31619200, 2019).
cancer (continued). "We found that phosphorylation of STAT3 Y705 but not S727 promoted cancer cell EMT and metastasis through the Slug-mediated regulation of E-cadherin and Vimentin." (PMID 31597912, 2019). "The STAT3 S727 phosphorylation site is downstream of extracellular signal-regulated kinase (ERK), respectively of RAS and is responsible for mitochondrial survival in cancer studies." (PMID 31798458, 2019). "Importantly, IL-6/STAT3-mediated inhibition of miR-200c during transformation and EMT of breast and lung epithelial cancer cells has also been demonstrated by others." (PMID 31557902, 2019). "We also demonstrated that ITGA2 interacted with STAT3 and up-regulated the phosphorylation of STAT3; this interaction might involve the mechanism of ITGA2 inducing PD-L1 expression in cancer cells." (PMID 31818309, 2019). "As the loss of PTPRD activated both ERK and STAT3 signaling, a single specific inhibitor would not suffice in patients with PTPRD-silenced cancer." (PMID 31805999, 2019). "Indeed, by using the gene set enrichment analysis (GSEA) of hallmarks of cancer, the differentially expressed genes were enriched in categories involved in: TNFα signaling via NF-κB, inflammatory response, IL6 JAK/STAT3 signaling and apoptosis categories." (PMID 31533831, 2019). "Surprisingly, the higher level of FAK activation upon STAT3 inhibition did not correlated with the enhanced migratory capabilities of these cancer cells observed before." (PMID 31671408, 2019). "On the other hand, considering the crucial roles of STAT3 in various cancers, as a new downstream regulator gene of STAT3, FOXL2 may have an important function in cancer." (PMID 31221094, 2019). "Furthermore, it has been reported that Stat3 is also a client protein of HSP9039,40, therefore, implicating CD167a/HSP90 as a candidate regulator of Stat3 activation in our cancer model." (PMID 31086186, 2019). "Particularly, high level of activated STAT3 is observed in TNBC subtype, which is closely related to the promotion of cancer progression and metastasis, increased resistance to chemotherapy, and reduced overall survival rates in cancer patients." (PMID 31684051, 2019). "In YTHDF2-deficient cells, re-expression of wild-type YTHDF2 but not the catalytically inactive mutant offset the acquired cancer-promoting inflammatory phenotypes, and reduced both phosphorylation of STAT3 and stabilization of IL11 and SERPINE2 mRNAs." (PMID 31735169, 2019). "Thus, we should consider what is the detailed relationship between JAK2, STAT3, and FOXO3 in cancer cells." (PMID 31540495, 2019). "Blockade of STAT3 pathway represents an enticing approach because of its known capability to have an effect on inflammatory status of APC, and as shown in current study, to improve the anti-cancer immunity in NSCLC." (PMID 31511071, 2019). "Since MPC1 binds to mito-STAT3 and inhibits the phosphorylation of STAT3, we explored whether MPC1-mediated cancer cell progression depends on the downstream of the STAT3 pathway." (PMID 30770798, 2019). "Moreover, a number of target genes of miR-155 affect other cancer-related processes, such as cell growth and survival (CCND1 and GAB3), cell adhesion junction (ANKRD6 and SMAD2), proliferation (SOCS1 and STAT3), and apoptosis (TP53BP1)." (PMID 31744065, 2019).
cancer (continued). "STAT3-induced transcription of protein-coding genes has been widely reported in various types of cancers; however, the role of STAT3 in the transcription of non-coding genes, such as miRNAs, is relatively less studied." (PMID 30927925, 2019). "The survival rates in the si-STAT3 and AG490 groups were much lower, indicating that the STAT3 signaling pathway could affect the behavior of cancer cells in multiple ways." (PMID 31685825, 2019). "The lack of significant difference between the studied STAT3 expression and some of the molecules associated with different cancer features might be due to studied sample characteristics that could involve origin, heterogeneity, and cancer pathophysiological background." (PMID 31234597, 2019). "Remarkably, the STAT3 decoy potently inhibited the growth of STAT3-dependent cancer cell lines, but not NOKs." (PMID 31671769, 2019). "2-Methoxystypandrone was able to block STAT3 and NF-κB pathways by covalently interacting the upstream kinase JAK2 and IKK, inhibited cell growth/survival, and eventually induced apoptosis in human cancer cells." (PMID 30709346, 2019). "Compared to control media (CTRL) and fibroblast conditioned media without TGFβ pretreatment (CM), TGFβ‐CM activated STAT3 in cancer cells, an effect that was efficiently inhibited by 2G8 treatment of the fibroblasts (TGFβ‐CM + 2G8)." (PMID 31609088, 2019). "Collectively, our study demonstrated that DYRK1A could positively regulate the STAT3/EGFR/Met axis and DYRK1A suppression could enhance the anti‐cancer activity of AZD9291 via STAT3 pathway in EGFR wild‐type NSCLC cells." (PMID 31454149, 2019). "The suppression of the STAT3 signaling pathway, which targets both CCND1 and Bcl-2, led to down-regulation of the expression of both proteins, thereby inducing cellular apoptosis in cancer cells." (PMID 31718693, 2019). "Understanding these different responses to STAT signaling in cancer is important to further distinguish tumors that would benefit from STAT3 or STAT5 inhibitors and those that would not." (PMID 31557897, 2019). "Besides, STAT3 inhibition decreases the CD133+ cell proportion and subsequently, sensitizes cancer cells to apoptosis." (PMID 31569687, 2019). "Even though there is no previous evidence in the literature for CCL7 abolishing immunoglobulin expression specifically during cancer progression, it was reported that MSC–derived CCL2 suppresses plasma cell immunoglobulin production via STAT3 inactivation and PAX5 induction." (PMID 30764543, 2019). "As cancer recurrence can occur due to the proliferation and colonization of viable cancer cells after RT, we evaluated whether JAK2 knockdown and STAT3 inhibition are capable of blocking the clonogenic potential of surviving cells after RT." (PMID 31511084, 2019). "Inhibition of STAT3 activation can also lead to the inhibition of AKT activation, which also reflected our in vitro and in vivo findings, indicating multiple potential pathways for the anti-cancer activity of brevilin A." (PMID 31178739, 2019). "Furthermore, a recent study has shown that the blocking activation of STAT3 can reduce the expression of MMP2 and inhibit the invasion ability of cancer cells." (PMID 31546234, 2019). "Similarly, pro-inflammatory signals such as IL6 can cooperate with HH/GLI in promoting cancer growth via a molecular mechanism where GLI and the IL6/JAK2-activated transcription factor STAT3 bind and synergistically activate common HH-IL6 target genes." (PMID 30991683, 2019).
cancer (continued). "Furthermore, emerging studies have demonstrated and emphasized the importance of lncRNA SNHG16 in regulation of cancer-related signaling pathways, including Wnt/β-catenin, PI3K/Akt, and JAK2/STAT3 pathway." (PMID 31632195, 2019). "Notably, some natural products have been reported to inhibit STAT3 activity through the regulation of SHP-1 and/or SHP-2 in cancer cells." (PMID 31117333, 2019). "ERK inhibition by addition of U0126 to cancer cells counteracted bCAFs-CM protection against induction of cell death by ABT-737 whereas STAT-3 inhibition using Stattic did not (bottom)." (PMID 30631150, 2019). "To date, no STAT3 inhibitors have yet been approved to treat cancer by the Food and Drug Administration (FDA), but many early-phase clinical trials are ongoing." (PMID 31861597, 2019). "The identification of these non-transcriptional roles of STAT3 will hopefully inspire further studies that can result in more holistic strategies to target STAT3 in cancer treatment." (PMID 30127373, 2018). "We determined the ratios of phosphorylated (p) proteins to their unphosphorylated counterparts (pSTAT3 to STAT3, pERK1 to ERK1, pERK2 to ERK2, pJNK1 to JNK1, and pJNK2 to JNK2) so as to evaluate the therapeutic effects on cancer metastasis, using western blotting." (PMID 29794990, 2018). "STAT3 and FAK1 activation are reported to be important in multiple cancer types, including BC." (PMID 30197755, 2018). "The molecular mechanism of CXCR2 in cancer progression may include various signaling pathways such as mitogen-activated protein kinase (MAPK), phosphoinositide 3-kinase (PI3K), signal transducer and activator of transcription 3 (STAT3) and NF-κB pathways." (PMID 29515768, 2018). "Therefore, EGFR downstream proteins, such as signal transducer and activator of transcription 3 (STAT3), play a crucial role in activating Wnt signaling in colon and ovarian cancers." (PMID 30068339, 2018). "STAT3 is activated in GBM and cancer stem cells of other brain tumors." (PMID 29783757, 2018). "Multiple signaling pathways, including the Stat3 signaling pathway, help maintain stem cell programmes in normal cells as well as in cancer cells." (PMID 30297887, 2018). "Elevated level of IL-6 expression is associated with cancer cell proliferation, angiogenesis, and metastasis via fueling signal transducer and activator of transcription 3 (STAT3), mitogen-activated protein kinase (MAPK), and Akt signaling, thus promoting EMT and subsequent cancer metastasis." (PMID 29357946, 2018). "Taken together, DHA-induced cancer cell apoptosis may be mediated with excess ROS, activation of MAPKs, MKP-1, STAT3-NF-κB, Akt, and mTOR signaling and increased in cAMP/cGMP, TLR-4, and PPAR-α." (PMID 30400136, 2018). "Activated STAT3 then contributes to HCV replication by inhibiting host antiviral immune responses and regulating the antiapoptosis and cancer-related genes that may promote the HCV-induced HCC." (PMID 32201498, 2018). "Therefore, since both lactate and STAT3 activation can increase expression of CAIX, it is certainly possible that the effect of CAIX inhibitors on radiation sensitivity of cancer stem cells is due to the interactions of CAIX with lactate and STAT3." (PMID 29439394, 2018). "Although a number of inhibitors have been developed to directly inhibit STAT3 activity in preclinical studies, none of these direct inhibitors are currently in clinical studies for cancer treatment." (PMID 29849942, 2018). "Indeed, Runx1 stimulates Stat3 signaling in three epithelial cancer cell types through the transcriptional repression of a Stat3 inhibitor, SOCS3, which triggers cancer cell growth." (PMID 30026553, 2018). "Stat3 and Src/FAK/Rac1 signal are known as an vital role in controlling cell migration and invasion by regulating the expression level of genes included MMP2, 9 and it is established that the level of MMPs is positively related to cancer cell metastasis." (PMID 29423083, 2018).